MEX3B (mex-3 RNA binding family member B)
Description:
RNA-binding protein. May be involved in post-transcriptional regulatory mechanisms.
Synonyms: RKHD3; RNF195; DKFZp434J0617; MEX-3B
Tractability: PROTAC: ubiquitination databases record sites on it; its protein half-life has been measured.
Gene: Protein-coding gene on chromosome 15 (82,041,778 to 82,046,119, reverse strand). Ensembl gene ENSG00000183496.
Subcellular location: Nucleus; Cytoplasm; Cytoplasm, P-body; Cytoplasmic granule
Subcellular location (Human Protein Atlas): Cytosol; Nucleoplasm
Gene Ontology:
Molecular function: protein binding; RNA binding; calcium ion binding; nucleic acid binding
Biological process: protein autophosphorylation; protein phosphorylation
Cellular component: P-body; cytoplasm; nucleus
Genetic constraint (gnomAD): Loss-of-function variants: 16 observed, 12.55 expected, observed/expected ratio (o/e) 1.27, 90% interval 0.86 to 1.83. The synonymous counts are far from expectation, so gnomAD's model fits this gene poorly and the ratio says little. Missense variants: 839 observed, 773.92 expected, observed/expected ratio (o/e) 1.08, 90% interval 1.02 to 1.15. Synonymous variants: 498 observed, 343.99 expected, observed/expected ratio (o/e) 1.45, 90% interval 1.34 to 1.56.
Homologues: Orthologues: chimpanzee MEX3B (99% identical), macaque MEX3B (99% identical), pig MEX3B (99% identical), mouse Mex3b (98% identical), dog MEX3B (98% identical), rat Mex3b (97% identical), rabbit MEX3B (96% identical), guinea pig MEX3B (80% identical), zebrafish mex3b (73% identical), tropical clawed frog MEX3B (72% identical). Paralogues in human: MEX3D (53% identical), MEX3C (52% identical), MEX3A (45% identical).
Diseases named in the same sentence as MEX3B in open-access papers:
MEX3B is named in the same sentence as 11 diseases in open-access papers, as found by Europe PMC text mining. Sharing a sentence is not in itself a finding about the gene and the disease. The quoted sentences say what the papers report.
gastric cancer (5 papers, 2020 to 2024). A primary or metastatic malignant neoplasm involving the stomach. "In this regard, HOTAIR/Mex3b promotes gastric cancer tumorigenesis by inhibiting the RUNX3–Claudin1 tumor suppressive axis." (PMID 36899853, 2023). "Therefore, the interaction between HOTAIR and Mex3b can induce the ubiquitination of Runx3 protein and enhance the invasion ability of gastric cancer cells, and providing a potential therapeutic target for gastric cancer metastasis." (PMID 35813070, 2022). "Another study shows that lncRNA HOTAIR induces Runx3 ubiquitination through the interaction with Mex3b while enhancing gastric cancer (GC) cell proliferation." (PMID 34746238, 2021). "In human gastric cancer, suppressing MEX3B expression inhibits the ubiquitylation and degradation of RUNX3, while the interaction of lncRNA HOTAIR with RUNX3 promotes the MEX3B-dependent ubiquitylation and degradation of RUNX3." (PMID 38424632, 2024). "HOTAIR, through promoting Mex3b-dependent ubiquitination and degradation of RUNX3, suppresses Claudin1 expression to foster gastric cancer cell invasion and EMT." (PMID 36899853, 2023). "Mechanistically, HOTAIR complexes with Mex3b to ubiquitinate and degrade RUNX3 in gastric cancer cells, leading to increased cancer invasiveness." (PMID 36899853, 2023).
melanoma (4 papers, 2020 to 2023). A malignant, usually aggressive tumor composed of atypical, neoplastic melanocytes. "Increased MEX3B expression has also been associated with melanoma resistance to anti-PD-1 immunotherapy." (PMID 38304027, 2023). "According to the TCGA melanoma dataset, higher MEX3B expression is linked to lower cytolytic activity and reduced lymphocyte infiltration in patients with this type of skin cancer." (PMID 38304027, 2023). "In melanoma, MEX3B downregulation is associated with antibodies against programmed cell death 1 (PD-1), while overexpression of this protein can inhibit T cell-mediated tumour elimination." (PMID 36507941, 2023). "RNA-binding protein MEX3B was identified as a candidate protein whose overexpression in melanoma cells decreased their susceptibility to killing by autologous TIL in vitro suggesting that it mediates resistance to cancer immunotherapy." (PMID 32894202, 2020). "Analysis of anti-PD-1 treated melanoma patient tumor samples suggested that higher MEX3B expression is associated with resistance." (PMID 32894202, 2020). "Using melanoma as a model, lower expression of MEX-3B correlated with response to checkpoint blockade, with an antibody directed against the programed cell death 1 (PD-1) receptor, while MEX-3B overexpression inhibited T cell-mediated tumor elimination." (PMID 32717840, 2020). "Overexpression of MEX3B in melanoma cells decreased IFN-γ release by autologous TILs and downregulated HLA-A expression." (PMID 32894202, 2020). "In the literature, it was already reported that MEX-3B expression leads to a downregulation of HLA-A, thereby inhibiting cancer immunotherapy of anti-PD-1-treated melanoma patients." (PMID 32717840, 2020). "Our findings have the potential to lead to the development of therapeutic strategies targeting MEX3B in hope of overcoming immunoresistance and achieving better clinical outcomes for patients with melanoma treated with immunotherapy." (PMID 32894202, 2020). "Interestingly, overexpression of MEX-3B in melanoma cells can downregulate the expression of HLA-A2 by binding to the 3′ UTR of HLA-A, thereby, blocking the recognition and CD8+ CTL-mediated killing of tumor cells." (PMID 32717840, 2020).
large cell lung cancer (1 paper, 2023). "MEX3A was expressed in LUAD, LUSC and large cell lung cancer (LCLC); MEX3B was detected in LCLC; and MEX3D was expressed in LUAD." (PMID 36507941, 2023).
viral infection (1 paper, 2023). "We found that LPS and poly (I:C) increased the MEX3B expression in epithelial cells, indicating that bacterial and viral infection may decrease the expression of TGF-βR3 through MEX3B in CRS." (PMID 36976645, 2023).
tumor (9 papers, 2020 to 2025). "Downregulation of HLA-A expression by MEX3B is a novel mechanism for tumor cells to evade attack by T cells." (PMID 32894202, 2020). "MEX3B was positively correlated with tumour purity and CD4+ T cell and macrophage infiltration." (PMID 36507941, 2023). "Additionally, the RBP MEX3B was proven to mediate resistance to cancer immunotherapy by down-regulating HLA-A expression on the surface of tumor cells." (PMID 35954405, 2022). "For example, overexpression of MEX3B in tumors can reduce the lethality of tumor-infiltrating lymphocytes, thereby mediating tumor immunotherapy resistance; NONO promotes cancer proliferation by regulating SKP2 and E2F8, significantly affecting patient prognosis." (PMID 35647031, 2022). "Among these upregulated genes, Dennd4a, Nfil3, Hspa1b, Chac1, Ddit4, Mex3b, Lysmd3, and Zbtb10 are mainly involved in oxidative stress and inflammation response, whereas Plcxd2, Dusp1, Cep85l, and Dusp8 are generally considered as tumor‐suppressor genes by inhibiting proliferation of cancer cells." (PMID 40231790, 2025). "The results of the present study showed that MEX3B and MEX3C expression was positively related to tumour purity and CD8+ T cell and CD4+ T cell infiltration." (PMID 36507941, 2023). "The GNA14 expression level was found to be higher in the adjacent tissues than in the tumor tissues, whereas GLS and MEX3B expression was lower in the adjacent normal tissues." (PMID 38304027, 2023). "HOTAIR can bind to RUNX3 protein, which functions as a tumor suppressor in multiple malignancies, and promote the interaction between RUNX3 and the E3 ubiquitin ligase MEX3B, inducing degradation via MEX3B-mediated ubiquitination." (PMID 32928281, 2020). "In addition, TIMER analysis revealed that MEX3B and MEX3C were positively related to tumour purity and CD8+ T cell and CD4+ T cell infiltration." (PMID 36507941, 2023). "MEX3B and MEX3C were positively correlated with tumour purity, CD8+ T cells and CD4+ T cells." (PMID 36507941, 2023).
cancer (6 papers, 2022 to 2025). A tumor composed of atypical neoplastic, often pleomorphic cells that invade other tissues. "To explore the role of the MEX3 family in cancers, we used TCGA for pan-cancer analysis of the expression of MEX3A, MEX3B, MEX3C and MEX3D." (PMID 38914858, 2024).
infection (1 paper, 2019). The state of being infected such as from the introduction of a foreign agent such as serum, vaccine, antigenic substance or organism. "The expression of Tlr3 and its co-receptor Mex3B is unaltered by infection in epithelium, stroma, and non-PMN immune cells." (PMID 31554802, 2019).
MEX3B also shares sentences with these, for which no sentence is quoted: glioma (1 paper); heart disease (1); nasal polyps (1); skin cancer (1).